IGF1R (insulin like growth factor 1 receptor)
Diseases named in the same sentence as IGF1R in open-access papers (continued):
Sharing a sentence is not in itself a finding about the gene and the disease.
glioblastoma (continued). "Through paracrine IGF2/IGF-1R signaling, IGFBP6 regulates the growth of chemoresistant glioblastoma, which is produced by scilicet chemosensitive tumor cells, and is secreted, which slows the evolution of GBM." (PMID 36865549, 2023). "We have previously studied the effect of another inhibitor of IGF-1R, picropodophyllin (PPP), on glioblastoma cellular models, and determined that the molecular mechanism of cell death induced by this compound was not a caspase-dependent apoptosis." (PMID 33322337, 2020). "As a result, it will be necessary to validate the prognostic performance of IGF1R and PCBP2 in a larger independent cohort of glioblastoma." (PMID 32153627, 2019). "In this paper, we show that IGF-1R and PDGFR inhibition are powerful strategies for combating glioblastoma." (PMID 30200644, 2018). "This was especially evident in the amount of cell death in T98 cells, which indicates that cell death mechanisms triggered by IGF-1R inhibition and PDGFR inhibition are cooperative, confirming similar results already shown in glioblastoma." (PMID 30200644, 2018). "In fact, several clinical trials with IGF-1R inhibitors, including PPP, are currently ongoing for the treatment of glioblastoma." (PMID 30200644, 2018). "The role of IGF1R in pediatric cancers including EWS, ARMS, OS, synovial sarcoma, Wilms tumor, neuroblastoma, glioblastoma and medulloblastoma, has also been documented." (PMID 26173023, 2015). "Different types of cyto-chemokines are involved in the crosstalk between hAT-MSCs and BTICs (medulloblastoma and AT/RT: CXCR4/SDF-1, CCR5/RANTES, IL6R/IL-6 and IL8R/IL8; glioblastoma: CXCR4/SDF-1, IL6R/IL-6, IL8R/IL-8 and IGF1R/IGF-1)." (PMID 26076490, 2015). "In this review, the importance of glioblastoma multiforme in signaling pathways initiated by extracellular tyrosine kinase receptors such as EGFR, PDGFR and IGF-1R will be discussed." (PMID 24709958, 2014). "This study investigates whether Hypoxia-Inducible Factor 1 alpha (HIF1α) and Hypoxia-Inducible Factor 2 alpha (HIF2α) coordinately regulate insulin-like growth factor 1 receptor (IGF1R) expression, thereby influencing chemosensitivity in glioblastoma multiforme (GBM)." (PMID 40290443, 2025). "To this end, we used the human glioblastoma U-87 MG (U87) cell line to generate IGF1R-overexpressing cells with or without the receptor’s capacity to translocate to the nucleus." (PMID 35574033, 2022). "In vitro, IGF1R nuclear localization enhances glioblastoma cell motility and metabolism without affecting their proliferation." (PMID 35574033, 2022). "Specifically, they found that an IGF1/IGF1R inhibitor targeting YTHDF2-expressing cells could suppress GSC viability and the growth of glioblastoma in vivo in an m6A-dependent manner." (PMID 34381710, 2021). "Moreover, the IGF-1R signaling pathway is highly active in different types of human tumors, as is the case for metastatic melanoma, and is known to play a critical role in the transformation, growth and survival of glioblastoma multiforme (GBM) cells." (PMID 33322337, 2020). "Indeed, in human glioblastoma U373-MG cells, which are highly sensitive to ASM inhibition, we found there is a small fraction of IGF-1R localized in the DRM fractions (fraction #1–4)." (PMID 31142470, 2019). "We believe that inhibition of the signal transduction pathways initiated by IGF-1R and PDGFR could be a useful alternative strategy for glioblastoma." (PMID 30200644, 2018). "Aberrant signaling through insulin-like growth factor 1 receptor (IGF1R) and epidermal growth factor receptor (EGFR) drives glioblastoma (GBM) progression and therapy resistance." (PMID 42200352, 2026). "Therefore, the combination of agents that inhibit both the IGF-1R and the PDGFR pathways could contribute to improve the treatment of glioblastoma patients." (PMID 30200644, 2018).
rhabdomyosarcoma (55 papers, 2008 to 2025). A rare aggressive malignant mesenchymal neoplasm arising from skeletal muscle. "Another SFK family member, Yes, is implicated in resistance to IGF-1R inhibitors in rhabdomyosarcoma." (PMID 39608716, 2024). "The combination of the MEK inhibitor trametinib and the IGF1R monoclonal antibody ganitumab is effective in murine models of RAS-mutated rhabdomyosarcoma." (PMID 39001383, 2024). "Accordingly, progression of rhabdomyosarcoma tumors and resistance to IGF1R inhibition were associated with reactivation of Akt in spite of suppression of IGF1R action." (PMID 34440844, 2021). "Similarly, nuclear IGF1R localization in alveolar rhabdomyosarcoma was associated with an aggressive phenotype." (PMID 33918477, 2021). "IGF1R has also been shown to be associated with uPAR and to promote cellular invasion and migration in cancer cells of the pancreas and colon as well as of rhabdomyosarcoma cells in vitro." (PMID 27502396, 2016). "In patient-derived murine models of RAS-mutated rhabdomyosarcoma, the MEK inhibitor trametinib results in a modest reduction in tumour growth, which is further enhanced when combined with the synergistic IGF1-R inhibitor gatinutmab." (PMID 40983796, 2025). "We previously showed preclinical therapeutic synergy between a MEK inhibitor, trametinib, and a monoclonal antibody specific for IGF1R, ganitumab in RAS-mutated rhabdomyosarcoma." (PMID 39001383, 2024). "In our previous studies, we evaluated the efficacy of the combination of the MEK inhibitor, trametinib, with a monoclonal antibody specific for IGF1R, ganitumab, in RAS-mutated rhabdomyosarcoma." (PMID 39001383, 2024). "PDGFRs are known to cross-talk with IGR-1R in many cancers, and PDGFRβ acts as a bypass resistance pathway to IGF-1R inhibition in rhabdomyosarcoma." (PMID 36497233, 2022). "Microarray analysis demonstrated that IGF2 and IGF1R are both highly expressed in rhabdomyosarcoma cell lines, xenografts, and human tumor samples." (PMID 34440844, 2021). "Overall, IGF2 and IGF1R constitute a potent autocrine signalling axis, which promotes proliferation of rhabdomyosarcoma tumors." (PMID 34440844, 2021). "Anti-IGF1R agents were tested as monotherapy in clinical trials including rhabdomyosarcoma patients." (PMID 34440844, 2021). "Cell vaccines co-targeting HER2/neu and murine IGF1R induced the highest level of anti-IGF1R antibodies and nearly significantly delayed the onset of spontaneous rhabdomyosarcomas." (PMID 30979001, 2019). "Vaccination was administered in the preneoplastic stage to mice prone to develop HER2/neu-driven, IGF1R-dependent rhabdomyosarcoma." (PMID 30979001, 2019). "This is consistent with data for rhabdomyosarcomas, where sensitivity to IGF1R inhibitors was reversed by constitutively active AKT and, conversely, progression of in vivo tumour models was associated with AKT reactivation." (PMID 29160922, 2018). "IGF1R was found to be deregulated in rhabdomyosarcoma (RMS) where its expression increased consistently and, hence, is suggested as an initial factor responsible for oncogenic transformation of muscle cells." (PMID 30519366, 2018). "The importance of IGF1R action in progression of these tumors is underscored by studies showing that a monoclonal antibody against IGF1R inhibited the growth of rhabdomyosarcoma xenografts in mice." (PMID 29455671, 2018). "The finding that miR-378a-3p affects both IGF1R and the Akt pathway was confirmed in a study which found that overexpression of miR-378a-3p in rhabdomyosarcoma suppressed IGF1R expression and affected phosphorylation of the Akt protein." (PMID 26839547, 2015). "miR-378a-3p overexpression suppressed IGF1R expression in rhabdomyosarcoma-derived RH30 cells and decreased the phosphorylation level of AKT protein, which is known as a key signaling molecule in rhabdomyosarcoma." (PMID 26255816, 2015).
rhabdomyosarcoma (continued). "In rhabdomyosarcoma xenograft models, tumors that escaped IGF1R inhibition displayed reactivation of Akt despite sustained down regulation of IGF1R activity." (PMID 26402468, 2015). "A well known growth factor circuit implicated in the genesis of human rhabdomyosarcoma is based on coexpression of IGF2 and its receptor IGF1R, a feature shared also by the rhabdomyosarcoma of BALB-p53Neu mice." (PMID 24334679, 2014). "In pediatric tumors such as Wilms' tumor, rhabdomyosarcoma, and NB, IGF-1R overexpression presumably increases the cellular responsiveness to the IGFs in terms of proliferation and inhibition of apoptosis." (PMID 25362349, 2014). "For instance, the IGF1R TKI PPP inhibited rhabdomyosarcoma proliferation, chemotaxis and adhesion." (PMID 34440844, 2021). "Likewise, the platelet-derived growth factor receptor (PDGFRα) was shown to be present in nuclear fractions of alveolar rhabdomyosarcoma along with IGF1R." (PMID 33918477, 2021). "Interestingly, the combination of the anti-IGF1R mAb ganitumab with the SFKs inhibitor dasatinib is being currently tested in patients affected by rhabdomyosarcoma, both alveolar and embryonal subtypes (NCT03041701)." (PMID 34440844, 2021). "However, early clinical trials with IGF1R inhibitors have shown modest efficacy in rhabdomyosarcoma patients." (PMID 31426421, 2019). "Increased expression of IGF1R is also characteristic for rhabdomyosarcomas." (PMID 28793874, 2017). "While in certain cancers, including Ewing’s and rhabdomyosarcoma, tumor IGF1R levels were correlated with responsiveness to IGF1R-directed therapies, most clinical data seem to indicate that IGF1R expression levels, per se, do not predict sensitivity to IGF1R inhibition." (PMID 27446805, 2016). "Interestingly, AXL is also induced during acquired therapy resistance including against IGF-1R-targeted therapy in a rhabdomyosarcoma model." (PMID 25528764, 2014). "Because AXL is induced during resistance development to IGF-1R-targeted therapies in rhabdomyosarcomas, which may also be the case in ES, this further supports a rationale to target AXL in ES." (PMID 25528764, 2014). "Furthermore, IGF2, the potent ligand of IGF1R, is also overproduced in rhabdomyosarcomas." (PMID 28793874, 2017). "Neuroblastoma cells, like rhabdomyosarcoma cells, are sensitive to the inhibition of the RAS/MAPK and IGF1R/AKT/mTOR pathways." (PMID 39001383, 2024). "In parallel, preclinical studies demonstrated that IGF1R inhibition with either mAbs or TKIs activated YES kinase, a member of the SRC family tyrosine kinases (SFKs), as a resistance pathway in rhabdomyosarcoma cell lines and xenografts." (PMID 34440844, 2021). "The inhibition of the phosphorylation of IGF1R and AKT after incubation with ceritinib has been described in rhabdomyosarcoma, and a synergistic effect of ceritinib and dasatinib was observed." (PMID 31234291, 2019). "For example, the MYB–NFIB fusion in adenoid cystic carcinoma is regulated by IGF1R through an autocrine loop, and IGF1R is a downstream target of the EWSR1–WT1 and PAX3–FKHR fusions in desmoplastic small round cell tumors and alveolar rhabdomyosarcoma, respectively." (PMID 31426421, 2019). "We then investigated whether cell vaccines co-targeting HER2 and IGF1R could delay the onset of HER2-driven, IGF1R-dependent rhabdomyosarcoma and salivary carcinoma." (PMID 30979001, 2019). "Similarly, a combination of anti-IGF-1R and SRC therapies displayed enhanced antitumour activity in in vitro and in vivo models of rhabdomyosarcoma when compared to either drug alone." (PMID 29435137, 2018). "It should be noted that the rhabdomyosarcoma line, RH-30, has the same surface expression of IGF-1R and EGFR when examined by FACS (data not shown)." (PMID 23548153, 2013). "Though not yet confirmed to be prognostic in EWS, high levels of IGF-1R appear to confer sensitivity in rhabdomyosarcoma, and may serve as a valid prognostic biomarker for that cancer." (PMID 24212944, 2011).
myeloma (54 papers, 2009 to 2025). "Aberrant activation of the IGF1/IGF1R axis has been associated with worse prognosis in many tumors, including breast, colorectal, laryngeal, myeloma, and prostate." (PMID 26884344, 2017). "Thus, interaction between IGF-1 and IGF-1R is associated with angiogenesis and survival of myeloma cells, and IGF-1R is considered a therapeutic target." (PMID 33435539, 2021). "As a representative example, IGF1R, which encodes a major mediator of growth and survival in MM, and is located astride compartments A and B in NPCs, switched entirely to compartment A in both myeloma cell lines." (PMID 34372935, 2021). "Furthermore, FAK is activated by IGF-1-mediated association of integrin β1 with IGF-1R in multiple myeloma cells grown in culture." (PMID 31215459, 2019). "To understand how the inhibition of IKK2 and the IGF-1R antibody could cooperate to cause cell death in myeloma cells we then chose to focus on the two cells lines with the highest levels of IGF-1R, LP1 and RPMI8226." (PMID 21799925, 2011). "High expression of the receptor tyrosine kinase (RTK) insulin-like growth factor-1 receptor (IGF1R) and RTK mutations are associated with high-risk/worse prognosis in multiple myeloma (MM)." (PMID 38893258, 2024). "As a tumor suppressor, let-7b-5p inhibits growth and apoptosis by targeting IGF1R in multiple myeloma; let-7b-5p suppresses proliferation and motility by negatively modulating KIAA1377 in squamous cell carcinoma cells." (PMID 37019900, 2023). "Let-7b-5p has been shown to regulate proliferation and apoptosis in multiple myeloma by targeting IGF1R." (PMID 35111808, 2021). "IGF-1, which are secreted from BMSC and autocrined by MM cells, binds with IGF-1R, contributing to the proliferation of myeloma cells and CAM-DR." (PMID 33435539, 2021). "IGF1R-inhibition was selected due to its importance as myeloma growth factor and impact on patient survival." (PMID 31242924, 2019). "An important role of the IGF-1/IGF-1R for proliferation and survival of malignant cells was described in mulitple myeloma, mantle cell lymphoma as well as Hodgkin’s lymphoma." (PMID 28456850, 2017). "Previously, we demonstrated that picropodophyllin (PPP) suppresses the IGF-1R tyrosine kinase activity and has potent anti-myeloma activity both in human MM cells and the murine 5TMM models." (PMID 25008202, 2014). "In keeping with the observations discussed previously, together with Podar's studies in multiple myeloma and our results from the phospho-array assay, we suggest that IGF1R clathrin-endocytosis mainly regulates the RAS/RAF/MEK/ERK pathway in ES." (PMID 21611203, 2011). "The humanised form of an antagonistic anti-IGF-1R mAb (AVE1642) selectively inhibits the growth of CD45neg myeloma cells." (PMID 19165200, 2009). "For example, let-7b-5p can inhibit multiple myeloma by targeting IGF1R and may serve as a target for the treatment and amelioration of multiple myeloma." (PMID 40534860, 2025). "Linsitinib and carfilzomib showed enhanced anti-myeloma activity in six out of seven HMCL irrespective of the IGF1R mutation status." (PMID 38893258, 2024). "A pre-assembled complex consisting of Sdc1, inactive αvβ3 or αvβ5 integrin and inactive IGF-1R is found in fibroblasts, breast cancer and other carcinomas, multiple myeloma and activated vascular endothelial cells undergoing pathological angiogenesis and is likely found in many cancers." (PMID 34778093, 2021). "Notably, IGF-1R is amplified and is the top-ranking dependency in multiple myeloma as assessed by RNAi screens." (PMID 32228485, 2020). "High levels of IGF-1R, and/or its activating ligands IGF-1 and IGF-2 have been associated with various types of human cancer (e.g. multiple myeloma, breast, prostate, colon, lung, pancreas, Ewing’s sarcoma) and also found to correlate with increased invasiveness and metastatic potential." (PMID 31215459, 2019).
myeloma (continued). "In addition, the IGF1R was recently tested as novel therapeutic target in solid malignancies and in multiple myeloma where IGF1R inhibitors appear to overcome bortezomib resistance in the malignant plasma cell." (PMID 25786252, 2015). "Finally, the IGF-1R inhibitor OSI-906 synergized with bortezomib to enhance myeloma cell death and overcame bortezomib-resistance in vivo." (PMID 24252210, 2013). "We show that IGF1R mutations can impact IGF1R activation and/or downstream signaling and that the combination of the pIGF1R/pINSR inhibitor linsitinib with the second-generation proteasome inhibitor carfilzomib shows promising anti-myeloma activity, regardless of the IGF1R mutation status." (PMID 38893258, 2024). "Several key questions about this activation mechanism remain unanswered, including how clustering of Sdc1 activates IGF1-R independent of IGF1 ligand, how SSTNIGF1R blocks IGF1 stimulation of IGF-1R in myeloma and whether SSTNIGF1R blocks IGF1-induced IGF-1R activation in tumors other than myeloma." (PMID 34778093, 2021). "A human monoclonal antibody against IGF1R, figitumumab (also known as CP-751,871), was studied in a phase I trial (NCT01536145) in multiple myeloma patients." (PMID 39482533, 2024). "Perhaps the greatest impact of Sdc1-coupled IGF-1R on tumorigenesis is its role in tumor survival, revealed in myeloma cells that express high levels of Sdc1 (CD138) and constitutively active Sdc1-coupled IGF-1R." (PMID 34778093, 2021). "For example, in vitro work with human myeloma cells that showed synergy between bortezomib and AVE1642, a humanized anti-IGF-1R mAb, led to a phase I trial (NCT01233895) of AVE1642 alone and with bortezomib in advanced myeloma." (PMID 30544512, 2018). "Together, the combination of an IGF-1R inhibitor and an ABT-analogue displays synergistic anti-myeloma activity providing the rational for further (pre)clinical testing." (PMID 25008202, 2014). "Alternatively, knockdown of INSR also resulted in an increase in total IGF-1R expression in hTCEpi cells, which is consistent with the finding that the siRNA knockdown of INSR increases IGF-1R expression in human myeloma cells." (PMID 22879999, 2012). "In multiple myeloma (MM), we previously demonstrated that an antagonistic anti-IGF-1R mAb (EM164, also named mAVE1642) can selectively inhibit the growth of CD45neg human myeloma cell lines (HMCLs)." (PMID 19165200, 2009). "Although in principle GEP would have been applicable for target selection, attempts failed due to lack of compounds usable for personalized treatment, and suggested compounds like inhibitors of aurora kinase or IGF1R never made it to approval in myeloma." (PMID 38035078, 2023). "However, inhibition of IGF-1R by SSTNIGF1R prevents these inhibitory phosphorylation events, allowing ASK-1 autoactivation, its subsequent activation of JNK/SAPK, and entry of myeloma cells into apoptosis." (PMID 34778093, 2021). "For example, in the case of IGFR, a phase I trial with a monoclonal antibody against IGF-1R in patients with relapsed multiple myelomas did not provide satisfactory results." (PMID 34439182, 2021). "There has been much excitement over the use of IGF-1R inhibitors for the treatment of multiple myeloma but these have not progressed clinically." (PMID 32228485, 2020). "We incubated primary myeloma cells with IKK2 inhibitors or/and anti-IGF-1R antibody for 24 h." (PMID 21799925, 2011). "We previously demonstrated that EM164 selectively inhibits IGF-1R but not insulin signalling in myeloma cells." (PMID 19165200, 2009). "It is of interest to note that although SSTNIGF1R inhibits both IGF-1R and its downstream activation of the αvβ3 or αvβ5 integrin in endothelial and carcinoma cells, the integrin is not active in the myeloma cells, suggesting that it is IGF-1R alone that is required for the survival signaling." (PMID 34778093, 2021).